TNF (tumor necrosis factor)
Diseases named in the same sentence as TNF in open-access papers (continued):
Sharing a sentence is not in itself a finding about the gene and the disease.
tumor (continued). "EGFR is a key regulator of cell proliferation and survival, while TNF plays a dual role in promoting inflammation and remodeling of the tumor microenvironment." (PMID 41281432, 2025). "Elevated levels of IFN-γ, IL-12, IL-15, and IL-18 are linked to favorable CRC outcomes, while IL-4, IL-6, IL-17, TNF, TGF-β, and VEGF indicate tumor progression." (PMID 40297577, 2025). "LYZ activates macrophages to kill tumors and plays a role in tumor suppression; however, under chronic inflammation, LYZ releases proinflammatory factors (IL-6, TNF-α) to promote immunosuppression in the tumor microenvironment." (PMID 41384115, 2025). "MiR-21 influences this process by upregulating M2 markers (like CD206 and IL-10) and downregulating M1 markers (such as TNF-α and iNOS), thus driving macrophages toward the tumor-promoting M2 phenotype." (PMID 40330466, 2025). "Neuroinflammatory cytokines, particularly interleukins and tumor necrosis factor-alpha, play pivotal roles in this microenvironment, contributing to tumor progression and immune evasion." (PMID 40061139, 2025). "This bacterium secretes various cytokines, including IL-6, IL-8, TNF-α, and MCP-1, which induce chemotaxis and activate tumor-associated neutrophils." (PMID 39814702, 2025). "Blockade of STAB1 (with bexmarilimab) followed by transcriptomic analysis demonstrated that TAMs were reprogrammed to enhance production of IL1β, IFNγ, and TNFα; all pro-inflammatory and cytolytic killing of tumor cells." (PMID 41007347, 2025). "By blocking TNF-α with a specific inhibitor in combination with trastuzumab, the antitumor effect is restored through modulation of the immunosuppressive tumor microenvironment." (PMID 40303301, 2025). "This activation leads to the upregulation of pro-inflammatory cytokines, such as TNF-α and IL-6, contributing to development of the microenvironment that promotes tumor cell adhesion and invasion." (PMID 41050662, 2025). "N1 neutrophils secrete ROS, TNF-α, and other cytotoxic molecules that contribute to tumor cell killing." (PMID 40160820, 2025). "M1 macrophages secrete pro-inflammatory cytokines such as tumor necrosis factor-alpha (TNF-α) and interleukin-6 (IL-6), thereby playing a pivotal role in host defense against pathogens and tumor cells through the modulation of immune responses." (PMID 40710515, 2025). "Cytokines secreted by tumor cells, including interleukins (IL) and tumor necrosis factor (TNF), influence not only tumor cells but also osteoblasts, osteoclasts, and other bone cells, thereby promoting bone metastasis." (PMID 39816691, 2025). "Due to increased levels of IFN-γ and TNF-α secretion by sNK cells, these cells have a higher capacity to induce differentiation in tumor cells." (PMID 40890122, 2025). "In vivo, a significant reduction (~89%) in tumor burden and favorable modulation of inflammation, characterized by a decrease in pro‐inflammatory cytokines (TNF‐α, IFN‐γ, IL‐6, VEGF) and an increase in anti‐inflammatory IL‐10 was observed." (PMID 40908716, 2025). "NF-κB signaling is triggered in macrophages by tumor-derived cytokines such as TNF-α and IL-1β, further enhancing the production of IL-6 and IL-10, that further promote tissue remodeling and angiogenesis." (PMID 40160820, 2025). "Many tumor cells can also increase the expression of TNF-α, further leading to the release of various inflammatory mediators, suppression of T-cell anti-tumor activity, and angiogenesis, thereby inducing tumor cell proliferation and metastasis." (PMID 40418396, 2025). "Functional-wise, gene set variation analysis (GSVA) analysis links activated MCs to immunostimulatory TNFα/NFκB signaling and MHC I/II enrichment, while resting MCs are associated with angiogenesis, a process important for tumor growth." (PMID 41450739, 2025).
tumor (continued). "Previous studies have demonstrated that CD8+T cells can induce cell death via the perforin-granzyme pathway and the Fas/FasL death receptor pathway, as well as indirectly kill tumor cells by releasing TNF-α." (PMID 40169575, 2025). "IL-17 promotes an anti-tumor cytotoxic T cell response to enhance the antitumor effects, and TNF can stimulate the proliferation of other immune cells to limit tumor progression." (PMID 40874228, 2025). "cultured TILs express IFN-γ, IL-4, IL-5, TNFα, IL-8, IL-10- and, to a lesser extent, IL-2 mRNAs while, in the corresponding tumor samples only TNF-α, IL-8 and IL-10- transcripts were expressed." (PMID 40092980, 2025). "Inhibits tumor growth, induces tumor cell apoptosis, increases M1-type macrophages in tumor tissue, elevates TNF-α and IL-6, and reduces IL-10." (PMID 40766304, 2025). "Alternatively, TNF-α exhibits a dual role in cancer, acting as both a tumor suppressor and a tumor promoter depending on the context." (PMID 40430212, 2025). "Elevated levels of inflammatory cytokines such as IL-6 and TNF-α not only promote tumor growth but also suppress effective anti-tumor immune responses." (PMID 40028339, 2025). "Significant evidence suggests that cytokines and glucocorticoids are linked to a poorer prognosis in cancer patients.IL-6 and TNF-α play roles in all stages of tumor development, including formation, progression, and metastasis." (PMID 40098072, 2025). "When exposed to tumor cells or other stimuli, in vitro developed ieILC1‐like cells generated more interferon γ and tumor necrosis factor α, degranulated more, and killed tumor cells more efficiently than NK‐2‐like cells." (PMID 41403916, 2025). "Concurrently, tumour cells elevate stemness‐associated ribosomal proteins (RPS7, RPL8, RPL30), enabling evasion of TNF signalling‐mediated surveillance." (PMID 40770837, 2025). "An M1-like TAM population can promote T cell recruitment and function and directly attack tumor cells via iNOS and TNF." (PMID 41465516, 2025). "NKT cells exhibit direct cytotoxicity against tumor cells via the Fas/FasL pathway, leading to the release of perforin, granzyme B, and TNF-α." (PMID 40070843, 2025). "Beyond its anti-tumor effects, cordycepin exhibits robust anti-inflammatory properties by downregulating pro-inflammatory cytokines, such as IL-6 and TNF-α, which are often elevated in both skin cancer and inflammatory skin disorders." (PMID 39852004, 2025). "In OC patients, cytokine levels of tumor necrosis factor α (TNFα) and IL-6, which are involved in regulation of tumor progression via JAK/STAT3 pathway and are regulated by gut microbiome, were increased." (PMID 39762846, 2025). "They noticed that GNPs injected into mouse mammary carcinomas during combined hyperthermia therapy significantly reduced tumor growth, cancer cell survival, and tumor blood perfusion at TNF-α doses that were found to be toxic with GNPs treatment alone." (PMID 40242201, 2025). "Among these, immunocytokines incorporating IL-2, IL-12, or TNF have demonstrated the most favorable tumor-homing properties and antitumor activity." (PMID 41568361, 2025). "We examined the correlation between tumour Te‐EV m6A levels and TNF‐α and IL‐6 secretion by tumour Te‐EV‐treated dTHP‐1 cells." (PMID 40326665, 2025). "On the other hand, loss of PRDX1 in macrophages restrains M2 polarization and enhances T‐cell‐mediated anti‐tumor immunity by promoting the secretion of inflammatory factors (IL‐1β and TNFα) via activation of JAK‐STAT1/NF‐κB signaling pathways." (PMID 41306557, 2025). "When combined with chemotherapeutic agents like oxaliplatin or 5-fluorouracil, anti-TNF-α therapy has demonstrated synergistic effects that result in tumor regression in preclinical models." (PMID 40558596, 2025). "Inflammatory cytokines, such as TNF-α, IL-6, and IL-17, released by immune cells, activate multiple signaling cascades within tumor cells." (PMID 40729026, 2025).
tumor (continued). "In contrast, when analysed according to histological tumour grade, only TNF-α demonstrated a significant increase in expression in G1–2 and G3 tumours compared to PeIN (Mann–Whitney test, p < 0.05)." (PMID 41465261, 2025). "TNF-α, a pro-inflammatory cytokine produced by immune cells and tumor cells, exerts a double-edged sword role in cancer." (PMID 40563367, 2025). "During this immune activation period, the release of pro-inflammatory factors such as IL-1β and TNF-α can promote the migration of monocytes, neutrophils, and platelets, enhancing the action of immune cells against the tumor." (PMID 41440517, 2025). "In this study, we provide evidence that tumor-induced systemic inflammation activates NF-κB signaling in the hypothalamus, leading to upregulation of key pro-inflammatory genes (IL-1β, TNF-α and IL-6) within the CNS." (PMID 40993108, 2025). "Tumor necrosis factor-alpha (TNF-α) is a pro-inflammatory cytokine that can act as both a promoter and an inhibitor in tumors, impacting tumor progression." (PMID 41450917, 2025). "When comparing the concentrations of the measured factors between the subgroups (classified by tumor type) and the control group, differences were found for TNF-α (p = 0.007) and Fascin (p = 0.035)." (PMID 40507492, 2025). "Given the significant correlation observed between hearing impairment and elevated levels of tumor-secreted TNF-α and TWEAK in VS patients, we further analyzed the levels of these cytokines in the blood and perilymph of TB and control mice." (PMID 39923035, 2025). "In DC/HPV16 E7, silencing CAT2 in exosomes induces M1 differentiation, increasing IL-12 and TNF-α and curtailing tumor growth." (PMID 40264780, 2025). "Once engaged, activated T-cells release cytotoxic molecules like perforin and granzymes, along with pro-inflammatory cytokines (e.g., tumor necrosis factor alpha (TNFα), interleukin (IL)-6), at the tumor interface, leading to cancer cell lysis." (PMID 40507301, 2025). "Together, these results suggested that GDF15 promoted neutrophil recruitment and activation through a TNF-α-dependent paracrine loop, ultimately promoting tumor progression." (PMID 41035818, 2025). "Neutrophils can secrete IFN-γ and TNF-α, which activate macrophages and increase their ability to phagocytose tumor cells, present antigens, and secrete cytotoxic factors that inhibit tumor growth." (PMID 40486614, 2025). "Meanwhile, we performed flow cytometry to quantify cytokine production in tumor-infiltrating γδ T cells, including IL-17, TNF-α, IFN-γ, IL-4, IL-10, and TGF-β." (PMID 41055972, 2025). "Th1 can secret anti-tumor cytokines, such as IFN-γ, TNF-α, and IL-2, which play an important role in anti-tumor immunity." (PMID 41237175, 2025). "These T cells secrete cytokines such as IFN-γ and TNF-α, which induce cytotoxic effects on tumor cells." (PMID 40386563, 2025). "Pro-inflammatory cytokines such as IL-6 and TNF-α often dominate the microenvironment, promoting tumor proliferation and facilitating immune evasion." (PMID 40352941, 2025). "One is the classically activated M1-like macrophage, which promotes an anti-tumor immune response through the production of pro-inflammatory cytokines such as IL-12, IL-1, IL-6, and tumor necrosis factor (TNF)-α, thereby exerting tumor-suppressive effects." (PMID 40028336, 2025). "Manipulating TNF signaling is inherently complex, as it can lead to both tumor-promoting and tumor-suppressive effects." (PMID 41315176, 2025). "Key mediators such as IL-1β and TNF-α act as endogenous tumor promoters, driving angiogenesis, invasion, and metastasis." (PMID 41302515, 2025). "It was shown earlier that IFN-γ and TNF-α play significant roles in tumor differentiation, therefore, we treated hA549 with rh-IFN-γ and rh-TNF-α to determine the IFN-γ- and TNF-α-induced differentiation in hA549." (PMID 39851518, 2025).
tumor (continued). "In NK cells, the activation of NKG2D triggers a cytotoxic response against target cells and promote the release of cytotoxic substances such as IFN-γ, TNF-α, and granzymes from NK cells, thus mediating the clearance of tumor cells." (PMID 41301424, 2025). "There is evidence that chronic exposure to IFN or TNF can make tumor cells more resilient to those cytokines over time." (PMID 40227782, 2025). "The primary function of M1 macrophages is to enhance local inflammatory responses and recruit immune cells by secreting pro-inflammatory cytokines such as IL-1, IL-6, IL-12, IL-23, and TNF-α, thereby forming a strong anti-tumor immune defense." (PMID 40438115, 2025). "Aberrations in pathways such as KRAS signaling up, Myc Targets I, and TNF-Alpha signaling can create a tumor-promoting environment and lead to tumorigenesis." (PMID 39801521, 2025). "Although the mechanisms by which basophils contribute to tumor suppression are not fully understood, certain mediators (e.g., granzyme B and TNF-α) released by these cells have tumor-killing properties." (PMID 40873585, 2025). "TNF-α can activate the NF-κB pathway, which induces pro-inflammatory gene expression and promotes processes such as tumor cell invasion and angiogenesis." (PMID 41446797, 2025). "Emerging strategies aim to reprogram the TME by targeting SASP components, such as IL6, IL1β, and TNF-α, which promote tumor progression." (PMID 40781676, 2025). "The elevated IFN-γ secretion level and reduced levels of TNF-α and IL-6 detected in tumor tissues suggested that activated CIK cells infiltrated into tumors." (PMID 40539041, 2025). "Experimental studies have demonstrated that surgical trauma activates pro-inflammatory cytokines (e.g., IL-6, TNF-α) and matrix metalloproteinases (MMPs), promoting tumor cell migration and invasion." (PMID 40236990, 2025). "More importantly, TNF-α showed strong positive correlations with several tumor markers within the cancer cohort." (PMID 40299527, 2025). "Global databases revealed that TNF‐α was highly expressed in a variety of tumor types, including GBM." (PMID 39803280, 2025). "Upon activation, ILC1s generate and secrete IFN-γ and TNF-α, which can subsequently activate different groups of cells with anti-tumor activity, such as NK cells." (PMID 40497988, 2025). "The increased production of IFN-γ and TNF-α by TILs in response to tumor stimulation highlights their capacity to mount a robust cytokine-mediated anti-tumor response, a hallmark of effective TIL therapy." (PMID 40806287, 2025). "Intercellular communication analysis also indicated enhanced signaling of pro-tumor TNF, EGF, VEGF, FGF, and WNT among cells in the NT5E-positive group." (PMID 41487509, 2025). "Cytokine analysis further revealed that TNF-α and IL-1β—key effectors of NK-mediated tumor cell killing and pyroptosis—were substantially reduced in the absence of NK cells." (PMID 41239499, 2025). "By modulating the NF-κB pathway, AE can inhibit the expression of pro-inflammatory factors TNF-α and IL-6, hence lowering the inflammatory response in the tumor microenvironment and blocking tumor growth and metastasis." (PMID 41480347, 2025). "This target-selective phagocytic activity was associated with increased secretion of pro-inflammatory cytokines (IL-6, IL-1β, TNF-α, IL-12) following co-culture with tumor cells." (PMID 41388305, 2025). "Such substances trigger the production of ROS, the recruitment and activation of immune cells to release inflammatory factors, such as tumor necrosis factor (TNF-α) and interleukin-6 (IL-6), thus promoting tumor metastasis." (PMID 40677396, 2025). "They exhibit enhanced production of ROS, increased tumor cytotoxicity, and upregulation of pro-inflammatory cytokines such as TNF-α and IFN-γ." (PMID 40486614, 2025).
tumor (continued). "Lymphocytes exert antitumor effects by inducing cancer cell apoptosis and releasing cytokines like interferon (IFN)-γ and tumor necrosis factor (TNF)-α, which inhibit tumor growth and metastasis." (PMID 39524006, 2025). "GASTON-Mix accurately learns the domains of the tumor sample and identifies several spatial gradient patterns of hypoxia and TNF-α signaling that are localized to specific tumor domains." (PMID 40662777, 2025). "Research has demonstrated that bacteria function as natural immune adjuvants, enhancing anti‐tumour immune responses by inducing the secretion of inflammatory mediators such as TNF‐α, IFN‐γ, and IL‐12." (PMID 39801378, 2025). "Tumor Necrosis Factor Alpha (TNF-α), despite its name, can enhance tumor growth and dissemination by promoting migration within the tumor microenvironment." (PMID 40869161, 2025). "Tumor-related factors include inflammatory cytokines secreted by tumors, such as interleukin-6 (IL-6) and tumor necrosis factor-α (TNF-α), which activate the ubiquitin–proteasome system (UPS), accelerating muscle protein degradation." (PMID 41487675, 2025). "Increased production of several cytokines including IFN-γ and TNFα has been observed as well as a reduction of tumor volume in those preclinical tumor mouse model, supporting the therapeutic benefit of LAG-3 and PD-1 blockade." (PMID 41051510, 2025). "Adenosine also inhibits the ability of neutrophils to produce pro-inflammatory cytokines such as TNF-α and IL-1β, further contributing to an immunosuppressive environment that favors tumor growth." (PMID 40486614, 2025). "Studies have demonstrated that EBV can induce the secretion of pro-inflammatory cytokines, such as IL-6 and TNF-α, which promote cell survival, angiogenesis, and tumor invasiveness." (PMID 40110195, 2025). "Results indicated a strong correlation between SERPING1 overexpression and tumor proliferation, encompassing pathways such as the tumor necrosis factor (TNF) signaling pathway, cell cycle and DNA replication." (PMID 39962118, 2025). "The cytotoxic functions of CTLs, such as granzyme B, perforin, IFN-γ, FasL (CD95L), and TNF-⍺, are elevated by induced hyperthermia, as is Fas receptor presentation on tumor cells." (PMID 41375025, 2025). "The presentation of tumor-specific epitopes to DCs or macrophages triggers the release of inflammatory cytokines, such as IL-1β, IL-6, IL-12, and TNF-α, and the upregulation of CD80/86, which induces the formation of specific Th-1 cells and DC maturation." (PMID 41375025, 2025). "Recent studies show that supplementation with aronia products can improve inflammatory markers such as interleukin-6 and tumor necrosis factor alpha, highlighting its potential role in modulating the tumor microenvironment." (PMID 41515306, 2025). "By comparing the communication probability between top-ranking ligands secreted by tumor cells and receptors on subclusters of monocytes and macrophages, we found that tumor cells predominately communicate with TNF-α+ TAMs via IL34-CSF1R in BI PitNETs." (PMID 39865310, 2025). "TNBCvax vaccination significantly increased CD8+ T cell infiltration and also upregulated the anti-tumor key effector molecules such as TNFα, IFNγ, and Granzyme B expression." (PMID 40969744, 2025). "Particularly, a comparison of TNF-α levels in the perilymph, tumor-conditioned media, and blood of three VS patients revealed that only the patient with the highest in vitro tumor secretion capacity for TNF-α exhibited detectable TNF-α levels in the perilymph." (PMID 39923035, 2025). "Overexpression of FASN suppresses TNF-α signaling and impairs immune surveillance, promoting tumor progression." (PMID 41294748, 2025). "In tumor therapy, the enhanced permeability and retention (EPR) effect allows nanoparticles to passively accumulate more efficiently in tumor tissues, making them ideal carriers for delivering proinflammatory cytokines such as IL-2, IL-12, and TNFα." (PMID 40557148, 2025).